APC (APC regulator of Wnt signaling pathway)
Diseases named in the same sentence as APC in open-access papers (continued):
Sharing a sentence is not in itself a finding about the gene and the disease.
tumor (continued). "Multiple key negative regulators, such as GSK-3β, APC, and ICAT, have been found to be suppressed in cancer, which contributes to the promotion of tumor progression through regulation of the oncogenic Wnt/β-catenin pathway." (PMID 26992223, 2016). "Subgroup meta-analysis by geographical populations was performed for p16, RASSF1A, GSTP1, APC, RUNX3, SOCS1 and PRDM2 between HCC tumor tissues and adjacent tissues." (PMID 27835605, 2016). "An altered methylation pattern of APC, CDH13, MGMT, MLH1 and RUNX3 genes is a well recognized characteristic of CRC tumor cells." (PMID 26862732, 2016). "The subgroup meta-analysis by geographical populations was also performed for p16, APC, RUNX3 and PRDM2 between HCC tumor tissues and normal tissues." (PMID 27835605, 2016). "Here we report targeted exome-sequencing of 1,321 cancer-related genes on 468 tumour specimens, which identified a subset of 17 genes that best classify CRC, with APC playing a central role in predicting overall survival." (PMID 27302369, 2016). "McNemar’s test comparing methylation above this cut-off in tumor and normal tissues in CRC patients determined tumor methylation of APC to be significantly higher than normal colonic mucosa methylation (P < 1.0×10-6)." (PMID 26884349, 2016). "Pre-operative methylated APC together with methylated DAPK predicted shorter overall survival, possibly by reflecting higher tumor burden at diagnosis." (PMID 26764421, 2016). "Lastly, we find that APC−/− cells display higher Yorkie (YAP) activity than host cells and that this promotes tumor growth, in part via cell competition." (PMID 26853366, 2016). "Together with APC in the β-catenin destruction complex is a scaffold protein AXIN1, functioning as a tumour suppressor in cancer." (PMID 27429002, 2016). "The meta-analysis of p14, p15, p73, APC, SOCS1, MGMT, SFRP1, PRDM2, DAPK1, RARβ, IGF2 and hMLH1 genes methylation was performed between HCC tumor tissues vs adjacent tissues and HCC tumor tissues vs normal tissues." (PMID 27835605, 2016). "We were able to demonstrate that quantitative assay of total plasma DNA and APC/RASSF1A methylation levels can rapidly and simultaneously predict tumor response and toxicity to cisplatin-based chemotherapy in ALC patients." (PMID 26550041, 2015). "So before we can observe obvious symptoms and signs, most patients (82.4 %) can use APC and RASSF1A methylation assay after every chemotherapy cycle to predict tumor response." (PMID 26550041, 2015). "Such plasticity is thought to arise through interactions between aberrant signaling events, including persistent activation of the APC/β-catenin and KRAS/BRAF/ERK pathways, and the tumor microenvironment." (PMID 25699236, 2015). "In these cancers, the methylation of the promoter regions of tumor suppressor genes, such as CDH1, APC, MGMT, RASSF1A, GSTP1, p16 and RAR-β2, affect the activity of tumor suppressor genes, typically leading to transcriptional silencing." (PMID 24748968, 2014). "In the present report, we demonstrated for the first time that APC/Ccdh1 and APC/Ccdc20 regulate BRD7 protein stability and its anti-tumor function." (PMID 24840027, 2014).
tumor (continued). "When the overall survival was correlated with the methylation status of candidate tumor suppressor genes, it was found to be significantly shorter in patients with RASSF1A and APC methylation positive tumor." (PMID 24790823, 2014). "In order to obtain the methylation signal of the APC promoter, the MethyLight assay was used to detect the CpG island methylation level of the APC promoter in 57 pairs of HCC and matched non-tumor liver tissues." (PMID 24765201, 2014). "Components of this complex include the tumor suppressors AXIN and APC and the protein kinases CK1 and GSK3β." (PMID 24202444, 2013). "Gene-specific hypermethylation was first described for the RB gene in retinoblastoma and many other tumour suppressor genes have been reported as methylated in tumours, for example p16, VHL, MLH1, APC and E-cadherin." (PMID 22771539, 2013). "Thus, β-catenin degradation was inhibited due to inhibition of APC, and the Wnt/β-catenin pathway was then activated by nuclear β-catenin accumulation, which may activate transcription of downstream target genes to promote tumor invasion and metastasis." (PMID 24244294, 2013). "Axin has been characterized as a tumor-suppressor gene and plays a key role in inhibiting the canonical WNT-pathway by forming molecular complexes with other proteins such as GSK3 and APC." (PMID 22984505, 2012). "Specifically, lower expression of APC, DCC, and DSC2 and higher expression of MACC1 was observed in the tumor samples relative to the paired adjacent normal tissue in both the microarray and qPCR assays." (PMID 22363440, 2012). "Using the hair follicle as internal control (set at 100% positivity), the expression of SHH, APC and RASSF1A in tumor cells was significantly lower (all p-values <0.001)." (PMID 23284750, 2012). "In combination, the strongest pair is APC and MCAM, showing 78.3% frequency in tumours and 23.3% in normals." (PMID 22068818, 2012). "A total of 15 genes (AIM1, ARF, CCNA1, MGMT, hMLH1, PGP9.5, S100A2, APC, RAR-β2, ER-α, ER-β, MCAM, VGF, FKBP4 and SSBP2) were analysed for promoter methylation using QMSP in 57 tumour samples, comprising 43 SEs and 14 NSEs, and 23 NT samples." (PMID 22068818, 2012). "In contrast to common HCC the APC and CDH1 (E-cadherin) genes were found devoid of any DNA methylation in FLC, whereas the GSTπ1 gene showed comparable DNA methylation in tumor and surrounding tissue at a moderate level." (PMID 21060828, 2010). "Using TaqMan qRT-PCR, all tumours analyzed displayed lower RASSF1A mRNA expression and higher levels of total APC mRNA than normal parathyroid, the latter of which was largely conferred by augmented APC 1B transcription levels." (PMID 20208994, 2010). "In two previous studies that focused on methylation of individual tumor suppressor genes in IBC, we observed increased methylation frequencies for two genes, APC and RARβ2, by using quantitative methylation-specific PCR." (PMID 20830311, 2010). "Hypermethylation of APC, p16, and MLH1 genes in tumour tissue was found in 3 (10%), 4 (13%) and 6 (20%) patients, respectively, but not in normal colonic tissue." (PMID 19257893, 2009). "In the same specimens, three further genes, that is APC, RARB2, and RASSF1A, proved to be hypermethylated at similarly high frequencies, and also discriminated well between tumour and normal tissue." (PMID 15292941, 2004). "Six tumours showed partial LOH on 5q, enabling the candidate region to be localised to a 22 cM region proximal to APC, flanked by D5S424 and D5S644." (PMID 8679443, 1996).
tumor (continued). "Tumor number significantly differed between APC; KRAS without DSS vs. APC; KRAS with DSS (P < 0.01), and vs. APC with DSS (P < 0.01); a modest difference was also seen between APC; KRAS with DSS and APC with DSS (P = 0.03)." (PMID 41285904, 2025). "In APC; KRAS mut mice, DSS significantly increased tumor number and size in the proximal colon." (PMID 41285904, 2025). "The lack of the functionality in the APC gene, a crucial tumor suppressor, seems to be the main driver of early-onset CRC, in fact variations in APC gene have been reported in 70–80% of both sporadic and familial CRC cases." (PMID 41150213, 2025). "In this case, no mutations were identified in the APC gene; however, a KRAS mutation (p.G13C) was detected, indicating a potential role in tumor pathogenesis due to its high VAF." (PMID 39939466, 2025). "There were increased rates of APC methylation in high-grade tumors (p = 0.048) and, therefore, the implication of a correlation with the tumor’s aggressiveness, although no statistical correlation was observed between tumor stage and APC methylation rates." (PMID 40282460, 2025). "Most tumours (70%) had 2–4 truncal hits in recognised cancer driver genes, irrespective of their APC status." (PMID 39920335, 2025). "Mathematical modeling of tumor development with different APC genotypes substantiates the “just-right” APC inactivation model and suggests alterations in secondary WNT regulators enhance WNT activity in colorectal cancers with suboptimal APC genotypes." (PMID 41091816, 2025). "Consequently, miR-125b promotes EMT, tumor invasion and CXCR4 expression, thus generating a positive feedback that also involves the Wnt/β-catenin signaling since APC appears to be targeted by miR-125b." (PMID 40535722, 2025). "However, in APC-truncated cancer cells USP10 binds to β-catenin, increasing its stability which is critical for maintaining an undifferentiated tumour identity." (PMID 39443725, 2024). "Intriguingly, the presence of laterally spreading tumor (LST) lesions, while not extensively described in the context of FAP, emerges as a noteworthy phenomenon, despite the implication of APC mutations in its molecular pathogenesis." (PMID 39202742, 2024). "Moreover, we tested for a genetic interaction between APC truncation and USP10 in a tumour-like setting using the ApcQ8 hyperplasia model." (PMID 39443725, 2024). "This combination creates a positive feedback loop of PIN1 inhibition and APC/CCDH1 activation, which may lead to synergistic anti-tumor efficacy." (PMID 38622115, 2024). "The dynamic changes observed in key mutations such as BRAF, APC, GNAS, EGFR, and PIK3CA suggest that ctDNA analysis can offer unique insights into tumor evolution that are not captured by traditional tissue biopsies." (PMID 39796090, 2024). "High miR-19a expression correlates with elevated β-catenin levels and advanced tumor stages in CRC specimens, suggesting that targeting the miR-17-92 cluster may have therapeutic potential in colon cancers with abnormal APC/β-catenin signaling." (PMID 38534736, 2024). "No germline findings were reported, but whole APC gene deletion was suspected due to the low amplicon depth of the APC gene in both the tumor tissue and blood samples." (PMID 38548799, 2024).
tumor (continued). "Significantly, by combining Pin1 and CDK4 inhibitors to prevent APC/CCDH1 inactivation, the APC/CCDH1 induces the degradation of Pin1 and other mitotic proteins, forcing the cells into cell cycle arrest and triggering increased anti-tumor immune activity." (PMID 38727267, 2024). "Because most of the KRAS mutant CRCs also have APC mutation, we included both in our study cohorts and classify these cases into HES1 (+) and HES1 (−) groups according to the presence or absence of tumor nuclear expression of HES1." (PMID 37749297, 2023). "Several of these mutations have been identified at the splice acceptor/donor sites of APC, however they have not been detected in the tumor samples in this study." (PMID 37824459, 2023). "Pharmacologic inhibition of Wnt ligand signaling with the porcupine inhibitor LGK-974 or of degradation of destruction complex components with the tankyrase inhibitor G007-LK in three CAC PDXs (two Wnt wild-type, one APC-mutant) did not suppress tumor growth." (PMID 36611031, 2023). "PDOs 1–3 harbor different truncating APC mutations, all lacking the β-catenin inhibitory domain (CID) critical for pathological WNT activation and tumor transformation via USP7 binding." (PMID 36669491, 2023). "Here, using APC, we demonstrate that working with peptides can overcome these limitations and allows us to identify the precise residues responsible for oligomerization and LLPS of a large, multifunctional protein that is a major tumor suppressor." (PMID 37047451, 2023). "Two upregulated proteins, APC and HINT2, also emphasize a tumor-suppressive role." (PMID 37834160, 2023). "Likewise, TRIM39 E3 ligase inhibits APC/CCDH1‐mediated degradation of MOAP1 (Modulator of Apoptosis 1), a tumour suppressor that activates the pro‐apoptotic Bax protein." (PMID 36881608, 2023). "Although loss of function of SMAD4 does not directly initiate tumorigenesis, it can promote tumor progression initiated by other genes, such as APC." (PMID 36831263, 2023). "Therefore, truncated APC cannot form ASAD-20R3/5 interactions, which would remove such potential regulation and explain why, for instance, N-terminal fragments expressed in tumor cells stimulate the ASEF protein more efficiently." (PMID 37047451, 2023). "We found that APC and CTNNB1 somatic mutations do not significantly coexist with somatic mutations in other melanoma-associated genes after controlling for somatic tumor mutation burden." (PMID 34986841, 2022). "ZC3H13 and METTL14 were strongly related to APC (an antagonist of the Wnt signaling pathway), meaning that ZC3H13 and METTL14 are involved in the regulation of invasion, proliferation, and metastasis of tumor cells." (PMID 36261786, 2022). "Since AMER-1 acts as a scaffold protein that recruits APC to consist of the β-catenin destruction complex, we believe that IRF-2 functions as a tumor suppressor gene in GC and that the axis of IRF-2-AMER-1/β-catenin plays an important role in the phenotype of cell proliferation." (PMID 35115027, 2022). "Across the 470 tumor specimen cohort, we did not identify deep deletions in the APC gene (< 0.33 copies/mean_cancer)." (PMID 34986841, 2022). "We speculate that the structural relationships between ARMC4 and APC suggest potential similar functional roles for ARMC4 and APC in binding proteins and possibly similar functions as tumor suppressors." (PMID 35269880, 2022).
tumor (continued). "A risk classification model based on the immunohistochemical expression of three proteins (APC, FHIT, and HER2) and five pathological parameters (tumor stage, resected nodes, margins, location, and sex) accurately separates the patients with GC into three groups." (PMID 35402221, 2022). "In this study, mutations in the genes ARID1A, APC, ERBB4, NCOR1, PDGFRA, ATM, and CDKN2A were either non-recurrent or of very low frequency, while none of the 14 sequenced EP tumours harboured mutations in the genes HRAS, EGFR, or RB1." (PMID 34045664, 2022). "35% of tumor specimens with APC/CTNNB1 genetic aberrations did not harbor either BRAFV600/K601 or NRASQ61 mutations compared with 50% of tumor specimens without." (PMID 34986841, 2022). "As both APC and AOM/DSS tumors were induced by WNT signaling, increased cytoplasmic and nuclear staining for β-catenin was observed in tissue regions with characteristic tumor histologies." (PMID 35600339, 2022). "Importantly, recent studies have reported an abundance of ILC2s in human CRC, and that tumour-infiltrating ILC2s in human CRC express IL-17BR, which is mirrored in APC-mutant mice." (PMID 36263033, 2022). "APC/CTNNB1 mutations are associated with a worse outcome in stage IV melanoma and early brain metastases independent of tumor-infiltrating lymphocyte density." (PMID 34986841, 2022). "Baseline genomic alterations in circulating tumor DNA, including SMARCA2, MSH6, APC signaling pathway, and Wnt signaling pathway, might be associated with the risk of HPD." (PMID 34858840, 2021). "The p16 gene (CDKN2A), which is a tumor suppressor gene, can inhibit cyclin-dependent kinase D. Most of the tumor suppressors function as negative cytoplasmic regulators, such as adenomatous polyposis coli protein (APC) and tensin homolog (PTEN)." (PMID 33920054, 2021). "APC is a negative regulator of the WNT signalling pathway that when lost, allows β-catenin to accumulate in the nucleus and drive an oncogenic transcription programme leading to tumour formation." (PMID 33879799, 2021). "We cultured two APC deleted tumor-derived organoid lines, with and without a spontaneous mutation in the KRAS oncogene (abbreviated organoids line A and AK)." (PMID 33972635, 2021). "Notably, APC expression appeared more intense in HCT116 and SW480 starved primary tumor cells than in the proliferating ones." (PMID 34885156, 2021). "As APC is a well-established tumor suppressor and negative regulator of WNT signaling, the targeted organoids displayed WNT signaling-independent growth." (PMID 33459801, 2021). "We created the Neo-fs index—defined as the number of marker proteins with low expression among the five independent prognosticators (APC, NOTCH1, ARID1A, EYS, and filamin A)—to develop a simple, practical biomarker with potential prognostic or predictive value reflective of tumor biology." (PMID 33801954, 2021). "Besides these two important GC driver genes, APC and PTEN tumour suppressor driver genes, as well as KRAS and PIK3CA driver oncogenes, were also transversally mutated in both GC histotypes with frequencies below 15% across data sets." (PMID 33724653, 2021).